EZH2 (enhancer of zeste 2 polycomb repressive complex 2 subunit)
Diseases named in the same sentence as EZH2 in open-access papers (continued):
Sharing a sentence is not in itself a finding about the gene and the disease.
cancer (continued). "In this regard, it has been demonstrated that in breast cancer cells, the EZH2 protein caused an activation or repression of the NF-κB pathway depending on the estrogen receptor (ER) status of the cancer cells." (PMID 36430394, 2022). "Aberrant PRC2 activity has been associated with cancer and neurodevelopmental disorders, particularly with respect to the malfunction of sits catalytic subunit EZH2." (PMID 35645710, 2022). "Subsequently, an association between EZH2 levels with immune infiltration was analysed in 39 cancers derived from the TIMER database." (PMID 35659256, 2022). "EZH2 dysregulation specifically has been associated with particularly aggressive cancers and malignancies." (PMID 35795673, 2022). "Hyperactivation of EZH2 due to gain of function mutations or overexpression has also been reported in different types of cancer, leading to the development of different EZH2 inhibitors." (PMID 33922336, 2021). "Studies have confirmed that the role of Forkhead box transcription factor-1 (FOXO1) is linked to the role of EZH2 inhibitors in cancer." (PMID 34149432, 2021). "EZH2 has been reported to be associated with the cell cycle, angiogenesis and the capacity of cancer cells to proliferate and migrate." (PMID 34124072, 2021). "Mutation or over-expression of EZH2 is associated with many types of cancers (breast cancer, prostate cancer, melanoma, bladder cancer, etc.)." (PMID 34938735, 2021). "Later, the TMPRSS2:ERG fusion causes crucial for cancer progression events, disrupting lineage-specific differentiation of the prostate and potentiating EZH2-mediated dedifferentiation program." (PMID 34356101, 2021). "Activating mutations of EZH2 have been shown to lead to oncogenic transformation and proliferative dependency on EZH2 activity in cancer." (PMID 34067530, 2021). "The overexpression also caused a decrease in expression of cancer-promoting factors EZH2, DNMT1, FOXM1, EGFR, PCNA, AURKA, YAP1, and CDH2." (PMID 34595169, 2021). "EZH2 expression is regulated by various oncogenic transcription factors and cancer-associated non-coding RNA that are critical for cell proliferation, tumorigenesis, and stem cell maintenance." (PMID 33791221, 2021). "In summary, our findings uncover a previously unidentified role of ZMYND8 in regulating PRC2 activities and promoting a Polycomb-dependent to -independent switch of EZH2 functions in hypoxia-exposed or VHL-deficient cancer cells." (PMID 33593912, 2021). "Consistently, the mERG/EZH2 gene set (n = 540), was functionally associated with oncogenic pathways and features enriched in cancer most of them overlapping with the ERG/EZH2 gene set." (PMID 34230470, 2021). "Further studies have proved that EZH2 inhibitors cannot effectively induce PTEN-deficient cancer cell death, but they can be overcome by combination therapy with taxanes." (PMID 34149432, 2021). "GSK2816126 exhibits outstanding anticancer ability in EZH2 mutated malignant tumors and can be administered intravenously in preclinical experiments." (PMID 34001246, 2021). "Deep understanding of additional mechanisms underlying lncRNA-mediated EZH2 actions, as well as other key cancer-related genes and proteins, will heavily rely on continuous exploration by scientific researchers and the advance of research technologies." (PMID 34512145, 2021). "It was also found that mutations or aberrant upregulation of EZH2 occur frequently in human cancers." (PMID 33591945, 2021). "EZH2 and H3K27me3 are closely linked to the development and progression of various cancers, and EZH2 is also expected to be a desirable therapeutic target." (PMID 35186711, 2021). "Among KMTs, EZH2 has been reported to be overexpressed in various cancers, including MPM, and particularly to be associated with aggressiveness and poor prognosis." (PMID 34277422, 2021).
cancer (continued). "For example, the EZH2 expression level in BRCA is positively correlated with the infiltration level of cancer-associated fibroblasts (Rho = −0.202, P = 1.41e-10) based on the EPIC algorithm." (PMID 34381492, 2021). "EZH2 inhibition has been shown to be sufficient for tumourigenesis and is associated with the generation of CSCs in some cancers." (PMID 33197277, 2021). "Overexpression or functional acquired mutations of EZH2 promote cancer progression by enhancing the function of methyltransferase." (PMID 33761979, 2021). "Overexpression of EZH2 has been documented in numerous cancers and shown to be associated with aggressiveness, metastasis, and overall poor outcomes." (PMID 32840881, 2021). "In cancer cells facing glucose limitation, the expression of EZH2 was downregulated and EZH2 deficiency attenuated glucose-deprivation-induced cell death and cell cycle arrest." (PMID 34671029, 2021). "It was worth pointing out that such studies claimed synergistic effect between BRAF inhibitors and EZH2 inhibitors in a subset of cancers that had EZH2 amplification or gain-of-function mutations which led to re-distribution of H3K27me3." (PMID 33713851, 2021). "The role of EZH2 in tumorigenesis appears to be context-dependent, since both EZH2 overexpression and loss of function are associated with different types of cancer." (PMID 33845873, 2021). "Several studies demonstrated that EZH2, a mammalian histone methyltransferase, is emerging as one of the most important targets of miR-101: loss of miR-101 function induces the overexpression of EZH2, which is related to cancer evolution." (PMID 34442460, 2021). "For instance, enhancer of zeste homolog 2 (EZH2) is a histone methyltransferase in the polycomb repressive complex 2 (PRC2) that has been implicated in cancer propagation." (PMID 34361090, 2021). "EZH2, is frequently overexpressed or mutated in a wide variety of cancer, including solid and hematological cancer." (PMID 34857028, 2021). "The epigenetic imbalance between KDM6A and EZH2 has been observed in several cancer types due to loss-of-function mutation of KDM6A or gain-of-function mutation of EZH2." (PMID 34006303, 2021). "EED226 is effective in treating cancers susceptible to EZH2 inhibition, as well as cancers with a mutant EZH2 protein resistant to SAM-e competitive inhibitors." (PMID 34617019, 2021). "A variety of signaling pathways and transcriptional mechanisms have been linked to EZH2 overexpression in cancer." (PMID 34943970, 2021). "Latest reviews had concluded the role of EZH2 in the poor prognosis of a variety of cancers and the underlying potentiality of EZH2 inhibitors among cancer treatment." (PMID 34715776, 2021). "RePhine predicted that loss-of-function of EZH2/PRC2 reduces cancer cell sensitivity toward the BRAF inhibitor PLX4720." (PMID 33713851, 2021). "Both gene repressor (Polycomb-dependent) and activator (Polycomb-independent) functions of the Polycomb protein enhancer of zeste homolog 2 (EZH2) are implicated in cancer progression." (PMID 33593912, 2021). "Although contradictory at the first glance, our results align with still scarce but growing evidence, that loss of PRC2/EZH2 activity can drive or support the initiation and progression of cancers in a context-specific manner." (PMID 34845197, 2021). "Overexpression of EZH2 has been described in several cancer types and has been associated with poor prognosis and aggressive disease." (PMID 34638497, 2021). "Inhibition of EZH2 has been reported to be linked with enhanced NK and T cell effector activities in certain cancers, as well as with an increased expansion of myeloid-derived suppressor cells (MDSCs) and consequent suppression of antitumor immunity." (PMID 33922336, 2021). "The most enriched KEGG pathways associated with EZH2 were lysine degradation (hsa00310) and microRNAs in cancer (hsa05206)." (PMID 33658396, 2021).
cancer (continued). "Mounting evidence indicates that EZH2 is elevated in various cancers and associates with poor prognosis." (PMID 34512145, 2021). "In the past, some studies have linked the role of EZH2 with cancer cell metastasis and showed that targeting EZH2 reduces the metastatic burden." (PMID 33531586, 2021). "EZH2 is recurrently mutated in some cancers and highly expressed in others; activating mutations in the EZH2 gene promote cancer growth and progression through several mechanisms, including MHC-I downregulation." (PMID 34201655, 2021). "Abnormal functions of EZH2 are associated with many types of cancers, and EZH2 inhibitors serve as promising drug candidates." (PMID 33868295, 2021). "Mutation or overexpression of the EZH2 gene plays a critical role in the development of various cancers such as CRC, melanoma, ovarian cancer, and breast cancer." (PMID 35008250, 2021). "The authors postulated a possible mechanism that EZH2 suppression results in a loss of chromatin condensation, which makes DNA more accessible to cisplatin and leads to more efficient DNA damage and cancer cell death." (PMID 34680389, 2021). "Collectively, our data suggest that EZH2 is a member of the network of cancer metabolism and that EZH2 deficiency upregulates GLS expression and blocks the glucose-deprivation-induced inhibition of GLS transcription in glucose-sensitive cells." (PMID 34671029, 2021). "Deregulations of PHD finger protein 19 (PHF19) and enhancer of zeste 2 (Ezh2) implied in epigenetic regulation have been frequently associated with cancers." (PMID 35003347, 2021). "We also found a statistically positive correlation between EZH2 expression and cancer-associated fibroblasts for the TCGA tumors of BRCA, LUSC, and THYM." (PMID 34381492, 2021). "Frequent EZH2 over-expression has been associated with cancer, however, the underlying mechanism remains unelucidated." (PMID 32943993, 2020). "Several lines of evidence have implicated EZH2 in the development and progression of a variety of cancers." (PMID 34968293, 2020). "More detailed molecular analysis revealed that suppression of the cancer cells’ viability by NSC745885 treatment was indeed causatively linked to downregulation of EZH2." (PMID 32880874, 2020). "Accumulating studies have proved EZH2 dysregulation mediated by mutation and expression in diverse human cancers including AML." (PMID 31794134, 2020). "ARID1A loss-of-function mutations sensitize cancer cells towards inhibition of EZH2, ATR, PARP, HDAC6, and HSP90 (and others)." (PMID 32272809, 2020). "EZH2 inhibition in ARID1A mutated tumors acts in a synthetically lethal manner to inhibit cancer progression, revealing a therapeutic opportunity." (PMID 33344089, 2020). "It had been reported that high levels of EZH2 expression are associated with the invasion and metastasis of malignant tumors, such as breast cancers and non-small cell lung cancers." (PMID 32635336, 2020). "The EZH2 mutations found in endometrial and other cancers are predominantly gain of function mutations." (PMID 33732505, 2020). "EZH2 mutation or overexpression is detected in solid tumors and leukemia, and correlated with cancer metastasis." (PMID 32493414, 2020). "The frequent EZH2 overexpression found in human cancers is associated with more aggressive cancer phenotypes with poor prognosis." (PMID 33299646, 2020). "As another core component of PRC2, Enhancer of Zeste Homolog 2 (EZH2) has been implicated as an oncogenic driver in a variety of cancers, playing diverse roles in aiding the development and progression of malignancy." (PMID 32182803, 2020). "According to these findings, loss of EZH2 in cancer cells abrogated cell cycle arrest in G1 and G2/M upon treatment with DNA-damaging agents Adriamycin or etoposide." (PMID 32343689, 2020). "Multivariant analysis established that high EZH2 in cancer cells was associated with high risk for ALN metastases (p=0.004); T1 tumors were associated with low risk (p=0.037)." (PMID 33235571, 2020).
cancer (continued). "Additional support for an oncogenic role for EZH2 in cancer comes from the loss-of-function mutations of other cancer associated chromatin regulators that normally antagonize EZH2 activity." (PMID 33003334, 2020). "Somatic EZH2 mutations or amplifications are observed in many cancers, including prostate cancer, colon carcinoma and non-Hodgkin lymphoma." (PMID 32066746, 2020). "It was shown that EZH2-S21phospho exerts a “neomorphic” effect in cancer by switching EZH2’s role from PRC2-associated repressor to coactivator." (PMID 33327550, 2020). "The E2F1/DDX11/EZH2 represents a promising therapeutic target in the clinical management of HCC that is one of the leading causes of cancer-related death globally." (PMID 33614480, 2020). "Accumulating studies have proved the phenomenon of EZH2 dysregulation mediated by mutation and expression in diverse human cancers including AML." (PMID 31794134, 2020). "Enhancer of zeste homolog 2 (EZH2), a gene encoding histone methyltransferase, is often overexpressed in multiple cancer types." (PMID 32942545, 2020). "Further investigation of these combinational effects on different cancer types should provide a solid foundation for treating patients with hyperactive EZH2 mutations." (PMID 32906688, 2020). "The associations between EZH2 and cancer initiation, progression, metastasis, metabolism, drug resistance, and immunity regulation are key points discussed in this review." (PMID 32723346, 2020). "Overexpression of EZH2 in cancer is associated with unfavorable clinical characteristics and shorter patient survival." (PMID 32331331, 2020). "Mutation or overexpression of EZH2 has been linked to numerous types of cancer and EZH2 inhibitors are being evaluated in clinical trials as potential anti-cancer agents." (PMID 32547515, 2020). "EZH2 is associated with malignant transformation and is reported to facilitate cancer cell proliferation, metastasis, and cancer stem cell expansion 2-9." (PMID 32754259, 2020). "EZH2 plays a critical role in cell proliferation and its overexpression is associated with cancer metastasis and poor prognosis." (PMID 33217970, 2020). "Loss-of-function ARID1A mutations sensitized various cancer cells towards inhibition of EZH2, PARP, ATR, HSP90 and HDAC9 (and others)." (PMID 32272809, 2020). "In the present study, we found that Et-miRNAs inhibited the expression of EZH2 and proliferation of cancer cells, while reduction of EZH2 caused the increase in Et-miRNA." (PMID 33718109, 2020). "Multivariate analysis detected that ALN metastases were significantly associated with high expression of EZH2 in cancer cells (p=0.004), and T1 stage had a low risk for ALN involvement (p=0.037)." (PMID 33235571, 2020). "EZH2 is frequently over-expressed in a variety of cancers and its over-expression has been implicated in the down-regulation of RUNX3." (PMID 32943993, 2020). "Treatment of SAHA also caused significant decline in cell number in carcinoma cells when used synergistically with EZH2 siRNA; conversely, the expression of EZH2 and HDAC1/2 were decreased by SAHA treatment in TGBC2TKB cells." (PMID 32210140, 2020). "Our recent study demonstrated that cancer cells harboring MLL3 PHD mutations are more sensitive to the depletion of EZH2, SUZ12, and EED in the PRC2 complex." (PMID 31747960, 2019). "Consistently, mutated H3 or EZH2 perform aberrant H3K27me3 redistribution, inhibit cell differentiation and support the generation of cancer." (PMID 31143370, 2019). "Epigenetic regulators, such as EZH2, are frequently mutated in cancer, and loss-of-function EZH2 mutations are common in myeloid malignancies." (PMID 30890554, 2019). "High expressions of EZH2 is associated with malignancy and hyper-invasiveness in a variety of cancers." (PMID 30881302, 2019). "In view of the high rate of EZH2 mutation in certain cancers, the application of these inhibitors in the clinic is expected to be successful in the future." (PMID 30984620, 2019).
cancer (continued). "This evidence suggested that NFATc2 is functionally linked to FOXM1 and EZH2, two genes known to regulate mesenchymal programs in cancer cells." (PMID 30710146, 2019). "Most importantly, we demonstrate that EZH2 inhibitor cannot effectively induce death in PTEN-deficient cancer cells, but this can be overcome by co-treatment with taxane." (PMID 31410199, 2019). "The overexpression of enhancer of zeste homolog 2 (EZH2) protein (histone methyltransferase) is associated with the aggressiveness of some cancers." (PMID 31752198, 2019). "Loss-of-function somatic alterations in genes encoding PRC2 subunits other than EZH2 also occur in tumors, and lysine residue 27 of histone H3 has itself been found to harbor specific recurrent missense mutations in highly restricted cancer types." (PMID 31097014, 2019). "We further show that PTEN-mutated cancer cells are resistant to EZH2 inhibitor-mediated killing, but the resistance can be overcome by docetaxel-induced nuclear localization of FOXO1." (PMID 31410199, 2019). "First, several studies have implicated PRC2 complex components including EZH2 in the pathogenesis of diverse cancers including hematopoietic malignancies." (PMID 31552175, 2019). "Rationale: The Polycomb group (PcG) protein EZH2 is implicated in cancer progression due to its frequent overexpression in many cancer types and therefore is a promising therapeutic target." (PMID 31410199, 2019). "Acquired chemo-resistance in cancer cells is also associated with EZH2 overexpression that enriches for cells with stem cell-like features." (PMID 30692641, 2019). "In several cancer models, EZH2 was proven to be associated with CDH1 transcriptional silencing and the mesenchymal phenotype." (PMID 30642115, 2019). "Chemo-resistant cancer cells are a growing problem, and many of them harbor mutations in EZH2 or PRC related genes." (PMID 29710783, 2018). "In the original set, EZH2 mRNA levels were significantly associated with cancer stage (p = 0.043) and recurrence (p = 0.016)." (PMID 30469511, 2018). "Although EZH2 seems generally associated to aggressiveness, some inactivating mutations or deletions of the EZH2 gene have also been reported in different cancers, suggesting an ambiguous role of EZH2 in these cancers." (PMID 34991274, 2018). "Aberrant Ezh2 expression occurs in many other solid tumors, but its effects and underlying mechanism in these cancers are currently unclear." (PMID 29335012, 2018). "EZH2, encoding a histone methyltransferase, is dysregulated in many cancers, but it is unclear if the disruption of this gene in a subset of DFT1s has provided a selective advantage to this lineage." (PMID 29634948, 2018). "Here we must mention the striking difference in cancer cells compared to ESCs and iPSCs, in which EZH2 expression and histone deacetylation are associated with differentiation, that is, with a decrease of the proliferation." (PMID 29853899, 2018). "They suggest BCL2 inhibition alone or in combination with EZH2 inhibition represents urgently needed therapeutic strategy for ARID1A-mutated cancers." (PMID 30297712, 2018). "A growing number of data suggests that overexpression of EZH2 associates with progression and poor outcome in a large number of cancer cases." (PMID 30510924, 2018). "While EZH2 has a role in normal cellular and tissue function, studies involving EZH2 overexpression or genetic mutations show that EZH2 is critical in the development and progression of a variety of cancers." (PMID 30619315, 2018). "Overexpression of H3K27me3 caused by activating mutation or overactivity of Enhancer of zeste homolog 2 (EZH2), a histone methyltransferase and a catalytic component of polycomb repressive complex 2, is a frequent event in many types of cancer." (PMID 30356299, 2018). "EZH2 activity is upregulated in cancer due to gain-of-function mutations, and overexpression by transcriptional, post-transcriptional and post-translational regulation." (PMID 29556394, 2018).